RELN (reelin)
Diseases named in the same sentence as RELN in open-access papers (continued):
Sharing a sentence is not in itself a finding about the gene and the disease.
cancer (continued). "Reelin contributes to cancer progression by activating integrin β1/Syk/Akt and STAT3 pathways and promoting cell adhesion, survival, proliferation, and drug resistance." (PMID 28345605, 2017). "In recent years, it has been established that reelin could also play a decisive role in tumorigenesis inside and outside the central nervous system, as the expression of reelin is frequently altered in cancer." (PMID 38543187, 2024). "However, the literature reveals a multifaceted role for Reelin in cancer development, with studies suggesting both promotional and inhibitory effects on malignant cell behavior depending on the cell type and affected organ." (PMID 38607022, 2024). "Collectively, by leveraging genomic profiles and clinical information, RELN mutations were determined as a potential biomarker for ICI treatment efficacy prediction, which may provide some clues for selecting cancer patients to receive immunotherapies." (PMID 36497098, 2022). "A number of studies have revealed changes in the expression of RELN in different cancer types." (PMID 36497098, 2022). "Interestingly, a number of studies has reported changes in the expression of reelin in different cancer types even outside the nervous system." (PMID 34205192, 2021). "Furthermore, expression of reelin in HER2-positive cancer cell lines co-cultured with astrocytes had increased proliferation which was reversed with the knockdown of reelin and HER245." (PMID 34521857, 2021). "Therefore, in the present study, we focused on the expression pattern of Reelin in OSCC, including tumor cells (ReelinTC), cancer-associated fibroblasts (ReelinCAF), and tumor-infiltrating lymphocytes (ReelinTIL)." (PMID 34485127, 2021). "Taken together, our data indicate that the expression of reelin in GBM may represent a potential contribution to the regulation of GBM cancer stem cells behavior, further stimulating the interest on the reelin pathway as a potential target for GBM treatment." (PMID 34205192, 2021). "Together, these findings suggest a cancer-suppressive role for Reelin." (PMID 33477804, 2021). "Thus, despite RELN being the most frequently mutated gene in our analysis, and epigenetic silencing of RELN being previously shown in several cancers, we decided to pursue RELN as a candidate gene." (PMID 27283491, 2016). "In clinical data sets, we evaluated expression of the human Reelin gene (RELN) in various cancer cell types using microarray data from Oncomine to assess whether RELN expression is reduced in cancers." (PMID 27071537, 2016). "Collectively, these data suggest that overexpression of FOXC2 and CLIP4 likely increases cell migration, which correlates to the synchronous metastasis of early-stage RCCs, whereas RELN may aid cancer cell survival." (PMID 27283491, 2016). "Ways to re-express Reelin in tumours, or to suppress Rac activation in tumours lacking Reelin expression, might be explored as a therapeutic approach to reduce cancer cell migration and to improve patient outcome." (PMID 27071537, 2016). "Also, Reelin has been proposed as a pro-metastatic factor due to their role in cancer cell migration through TGF-β pathway activation." (PMID 24597571, 2014). "Reelin (RELN), which is a glycoprotein secreted by Cajal-Retzius cells of the developing cerebral cortex, plays an important role in neuronal migration, but its role in cell migration and cancer metastasis is largely unclear." (PMID 22393371, 2012). "They both regulate reelin signaling pathway to induce apoptosis in cancer cells through as yet unknown mechanisms." (PMID 22905152, 2012). "Reelin was reported to be important in neural development and cancer metastasis, thus we speculated that Reelin might be involved in TGF-β1-induced cell migration." (PMID 22393371, 2012). "Four clusters were established labeled as cancer, development, Alzheimer and Reelin respectively." (PMID 16438716, 2006).
cancer (continued). "Therefore, dedicated studies should assess whether cancer might represent a medical contraindication for future anti-Reelin therapies." (PMID 38607022, 2024). "Therefore, it is possible that neuron-like BrM cancer cells can also express reelin." (PMID 37728789, 2023). "In addition to tissue homeostasis, reelin might have a role in diseases since altered expressions of reelin have been found in several pathologies, including cancer." (PMID 36290310, 2022). "However, the expression of Reelin in different cancers was different." (PMID 34485127, 2021). "Thus, high levels of Reelin in the brain may serve as a catalyst for cancer progression." (PMID 40506610, 2025). "The WNT signalling pathway, cancer-related pathways, VEGF signalling pathway, and MAPK signalling pathway were significantly enriched in the RELN-related phenotype." (PMID 38307969, 2024). "In this pathway, the role of reelin is pivotal, as reelin was found to be directly regulated by a key epigenetic modulator, SMARCD3, to launch a cascade of factors that trigger cancer cell metastasis." (PMID 37728789, 2023). "Most genes that were found to be upregulated in younger patients are involved in important signaling pathways that promote cancer progression and metastasis, such as MAPK pathway, Reelin pathway and the PI3K/Akt pathway." (PMID 36685821, 2022). "We checked mTOR expression in wt and yotari livers since reelin activates PI3K/Akt/mTOR, a pathway that is often hyperactivated in cancers." (PMID 34639052, 2021). "Our results provide the first evidence linking Reelin to TGF-β signal pathway, which contribute to cancer metastasis, and it is helpful for anti-cancer strategies." (PMID 22393371, 2012). "Of note, no increased mortality or cancer occurrence was reported in the Reelin KO mice compared to WT." (PMID 38607022, 2024). "Three of these genes (RELN, IRS2, and FOXP1) have a known association with non-CRC digestive cancers and one (RRAS2) has a known association with non-CRC cancer." (PMID 37627102, 2023). "The following most altered cancer genes were LRP1B (26%), PIK3CA (24%), CDKN2A (24%), PTPRD (15%), RB1 (13%), PDE4DIP (13%), PCLO (11%), KRAS (11%), FAT1 (10%), and RELN (10%), and these results partially overlap with the most altered genes depicted in the experimental cohort." (PMID 35330454, 2022). "From the differential genes involved in these pathways, we identified several gene clusters uniquely upregulated in the CAFWPOI 4-5 type; neuronal development and function-related (RELN, MYH10, CACNB4, OXTR, CAV3, CHRM2) and inflammation and cancer-related (RELN, IL21R, EDNRB, CAV3, OXTR)." (PMID 36045118, 2022). "Our results provide the first evidence that Reelin was involved in TGF-β signal pathway, which contributes to cancer metastasis and could be useful for anti-cancer strategies." (PMID 22393371, 2012). "Given that CDC42-GTP promotes F-actin polymerization and filopodia formation, facilitating cancer cell migration and survival at distant metastatic sites, we found that Reelin treatment upregulated GTP-CDC42 in control cells, with no change observed in LRP8 knockdown cells." (PMID 40506610, 2025). "Based in these observations, it can be suggested that reelin mRNA increases in the adjacent areas in response to the damage that might progress to cancer, but this change does not occur as long as reelin is present." (PMID 36290310, 2022). "The set of genes proximate to these IS was significantly enriched in two datasets of cancer genes, including cancer drivers (genes such as BRAF, PIK3R1, RELN and TIAM2) suggesting that some koalas may harbour ERVs that could confer increased cancer susceptibility." (PMID 33637755, 2021). "Whether Reelin/integrin β1/FAK pathway contributes to the Warburg effect in cancer cells is not known." (PMID 28345605, 2017).
cancer (continued). "Therefore, the correlation of Reelin and TGF-β pathway was critical in cancer metastasis, and Reelin could be one potential anti-metastasis target in future clinical practice." (PMID 22393371, 2012). "We also hypothesized that the microenvironment accompanying the colon lesion could change the epithelial myofibroblasts from cells expressing high reelin (inflammation), which protects against pathology, to those producing less or no reelin, which would allow for cancer development." (PMID 36290310, 2022). "Nowadays, multiple studies have addressed the role of reelin signaling in embryonic nonneuronal tissues such as the development of odontoblasts, small intestine, lymphatic vasculature, mammary gland, submandibular gland, cartilage and bone, as well as diseases and cancers in adulthood." (PMID 34639052, 2021). "Notably, alterations in Reelin expression are observed in cancers of nonneuronal origin." (PMID 34485127, 2021).
psychiatric disorder (46 papers, 2010 to 2025). A disorder characterized by behavioral and/or psychological abnormalities, often accompanied by physical symptoms. "Abnormal expression of reelin has been linked to various psychiatric disorders, highlighting the importance of this process for proper brain function." (PMID 39064075, 2024). "An ethnicity-based subgroup analysis of a meta-analysis found that the single-nucleotide polymorphism (SNP) rs736707 in the RELN gene correlated with psychiatric disorders, including ASD, in an Asian group." (PMID 35163751, 2022). "The methylation of RELN gene is thought to most likely be an important factor in the regulation of RELN expression and the is also thought to be associated with psychiatric disorders." (PMID 34831111, 2021). "Results of genetic studies have suggested that the Reelin gene (RELN) is associated with psychiatric disorders, including schizophrenia (SCZ) and autism spectrum disorder." (PMID 30158644, 2018). "Reelin depletion and stress seem to affect similar pathways including GABAergic and glutamatergic signaling and both are implicated in psychiatric disorders in late adolescence/early adulthood." (PMID 29941797, 2018). "Results from genetic studies have suggested that RELN is associated with the risk of psychiatric disorders, including schizophrenia (SCZ)." (PMID 30158644, 2018). "The extracellular matrix protein reelin which contributes to cellular and network plasticity, is a risk factor for several psychiatric diseases." (PMID 27765946, 2016). "Several reports have implicated reelin signaling in the etiology of neurodevelopmental and psychiatric disorders." (PMID 23110844, 2012). "Understanding how reelin activity is associated with symptom manifestation opens the way to uncovering the complex molecular dynamics contributing to the symptomatic aspects of this complex mental disorder." (PMID 39064075, 2024). "In previous studies we reported that TgRln mice were more resilient to stressors implicated in the genesis of psychiatric diseases (chronic stress and psychostimulant administration), suggesting a role for Reelin in preventing behavioral symptoms related with these disorders." (PMID 37153634, 2023). "Clinical studies showed reductions in Reelin protein and mRNA expression levels in patients with psychiatric disorders; however, the causal relationship remains unclear." (PMID 35163751, 2022). "Perturbations in reelin signaling are linked to psychiatric disorders." (PMID 31831824, 2019). "RELN has also been associated with psychiatric disease in several contexts." (PMID 28165338, 2017). "Reelin is a signaling glycoprotein serving multiple functions in the brain throughout life which has also emerged as a psychiatric risk factor in a wide spectrum of psychiatric disorders." (PMID 28127276, 2016). "The finding of reduced reelin levels in these disorders has prompted interest in the reeler mutant mouse, which has a spontaneous mutation in the reelin gene, as an animal model of neurodevelopmental and psychiatric disorders." (PMID 23110844, 2012). "Thus, reelin may serve as a neurobiological hub that underlies the development of psychiatric diseases." (PMID 39926699, 2025). "By contrast, Reelin deficiency during the developmental and early postnatal stages would severely affect the brain structure, which may be related to the development of some types of young-onset mental disorders." (PMID 27803648, 2016). "Thus, in regard to the epigenetic regulation of RELN expression, further investigation is needed to confirm the association of hypermethylation in the RELN promoter region with the predisposition to major mental illnesses." (PMID 27803648, 2016). "DAB1, a key component of the Reelin pathway, is sufficient to induce behavioral deficits related to psychiatric disorders." (PMID 37029353, 2023).
psychiatric disorder (continued). "Conversely, overexpression of Reelin protects against psychiatric disease-related phenotypes in mice, since it reduces cocaine sensitization, disruption of pre-pulse inhibition (PPI) and the time spent floating in the forced swim test." (PMID 37153634, 2023). "Conversely, the overexpression of Reelin protects against psychiatric disease-related phenotypes in mice." (PMID 37891846, 2023). "Reelin (RELN) plays a significant role in the development of the brain, and connections have been seen between RELN dysfunction and psychiatric disorders." (PMID 31114610, 2019). "Here, we review evidence for a role of the epigenetic control of the expression of RELN in the regulation of neuronal plasticity and behavior in SZ and BP disorder patients compared with controls devoid of major psychiatric disorders." (PMID 27092053, 2016). "Further investigations are needed to elucidate the role of Reelin in the functions of the mPFC relevant to mental illnesses." (PMID 27803648, 2016). "To further clarify theconnection between reelin and psychiatric disorders, we studied the factors thatinfluence the expression of reelin gene (RELN) and itsdifferent isoforms." (PMID 21603580, 2011). "Reelin is a large extracellular matrix protein abundant in brain tissue whose levels are down-regulated in several psychiatric disorders." (PMID 20414372, 2010). "Since the amount of Reelin in serum fluctuates in psychiatric disorders, it may be used as a marker of illness and an indicator of therapeutic efficacy." (PMID 35163751, 2022). "Presumably, Reelin plays a significant role both in AD and in psychiatric disorders." (PMID 34681041, 2021). "Alterations in the Reelin signaling pathway have been described in different psychiatric disorders." (PMID 29049379, 2017). "To date, the role of reelin is still under investigation for several mental illnesses." (PMID 28387726, 2017). "However, the molecular abnormalities in the Reelin pathway involved in the pathogenesis of psychiatric disorders are not yet fully understood." (PMID 27803648, 2016). "In this article, we review the current progress in the understanding of the Reelin functions that could be related to the pathogenesis of psychiatric disorders." (PMID 27803648, 2016). "Furthermore, Reelin also regulates adult neurogenesis and synaptogenesis, whose disruption is considered to be involved in the pathogenesis of psychiatric disorders." (PMID 37153634, 2023). "Interestingly, pharmacological supplementation or genetic overexpression of Reelin, prevent some of these deficits (e.g., associative learning, sensorimotor gating) and support the idea of boosting Reelin levels as a therapeutic approach in psychiatric disorders." (PMID 37153634, 2023). "Thus, the elevated contribution of GluN2B in the adult PrPFC of HRM could be an aggravating factor for prefrontal dysfunction in psychiatric disorders related to reelin haploinsufficiency." (PMID 27765946, 2016). "This lack of consensus challenged the validity of a role of reelin dysfunctions in the etiology of psychiatric disorders." (PMID 27765946, 2016).
tumor (44 papers, 2010 to 2025). "Lipid rafts serve as dynamic hubs for integrating signaling events in both tumor and neuronal cells, including those associated with RELN and Wnt signaling." (PMID 40171042, 2025). "In line with reelin’s commonly reported function as a neuronal stop signal, the analysis of publicly available data sets suggests that the expression of reelin is negatively associated with both tumorigenicity and tumor grade." (PMID 38543187, 2024). "In OSCC, to investigate the association between Reelin and tumor proliferation, we analyzed Ki-67 among high- and low-expressed groups of Reelin." (PMID 34485127, 2021). "Extracellular matrix glycoprotein Reelin is associated with tumor metastasis and prognosis in various malignancies." (PMID 34433809, 2021). "Although the studies related to Reelin mainly focuses on brain development and tumor progression, some studies have proved that Reelin is also linked to immune function." (PMID 34485127, 2021). "RELN encodes reelin, a matrix serine protease regulating neural cell migration and tumour progression." (PMID 21081927, 2011). "However, Reelin was positively associated with tissue-resident B cells and NK cells in the tumor microenvironment." (PMID 34485127, 2021). "However, the database showed that Reelin was positively associated with tissue-resident B cells and NK cells in the tumor microenvironment, suggesting that Reelin regulates immune response depending on the tissue or blood microenvironment." (PMID 34485127, 2021). "In assessing the cytogenetic abnormalities in leukemic cells of patients with secondary AML, a strong correlation between the therapy response and mutations associated with primary chemoresistance, RELN(q22), and alteration of tumor suppression, TES(q31), was detected (r = 1.0 for both mutations)." (PMID 31067780, 2019). "In addition, high RELN expression was associated with higher numbers of tumor cells in the bone marrow (42.0% ± 24.9% for high RELN and 28.5% ± 22.8% for low RELN expressions, P = 0.029)." (PMID 26848618, 2016). "Besides the role of Reelin in normal physiological conditions, loss of Reelin expression has been linked to tumour development and metastasis formation." (PMID 27071537, 2016). "The association between reelin and cellular migration, both in the embryonic and adult life, led to the assumption that reelin could be involved in the proliferation and migration of tumor cells." (PMID 28255385, 2017). "However at later stages of disease other factors or additional mutations in the tumours could overtake the effect of RELN making this pathway less relevant." (PMID 27071537, 2016). "The most frequently mutated driver genes were RELN, CDH1 and ARID1A, identified in 75%, 65% and 40% of tumor samples, respectively." (PMID 36703611, 2023). "In this study, we found that the RELN gene was highly methylated in HCC tumor tissues and sorafenib-resistant HCC cells, and the demethylation of the RELN gene reversed the effect of sorafenib on HCC cells." (PMID 35034536, 2022). "CD209 (DC-SIGN), MARCO, and RELN genes function in the downregulation of the immune system through IL10 and inhibitory tumor-associated macrophage mechanisms respectively." (PMID 34349241, 2022). "After observing Reelin’s role in suppressing MM tumor growth, we investigated the changes of key proteins involved in bone lesions." (PMID 34433809, 2021). "In this study we observed a higher expression of reelin and Dab1 transcripts in both peritumoral area and peritumoral-derived CSCs, with respect to the tumor core." (PMID 34205192, 2021). "Reelin has a versatile function in distinct cell types during the development of OSCC via governing tumor cell and stroma microenvironment." (PMID 34485127, 2021). "Extracellular matrix protein Reelin was reported to participate in tumor cell progression, migration and adhesion, particularly in MM according to recent studies." (PMID 34433809, 2021).